APOC1 (apolipoprotein C1)
Description:
Inhibitor of lipoprotein binding to the low density lipoprotein (LDL) receptor, LDL receptor-related protein, and very low density lipoprotein (VLDL) receptor. Associates with high density lipoproteins (HDL) and the triacylglycerol-rich lipoproteins in the plasma and makes up about 10% of the protein of the VLDL and 2% of that of HDL. Appears to interfere directly with fatty acid uptake and is also the major plasma inhibitor of cholesteryl ester transfer protein (CETP). Binds free fatty acids and reduces their intracellular esterification. Modulates the interaction of APOE with beta-migrating VLDL and inhibits binding of beta-VLDL to the LDL receptor-related protein.
Synonyms: Apo-CI; ApoC-I; apo-CIB; apoC-IB; APOC1B
Tractability: Antibody: its Gene Ontology location is reachable by antibodies, with high confidence; UniProt places it where antibodies can reach, with medium confidence; UniProt predicts a signal peptide or a membrane-spanning region. PROTAC: its protein half-life has been measured.
Gene: Protein-coding gene on chromosome 19 (44,913,133 to 44,920,054, forward strand). Ensembl gene ENSG00000130208.
Subcellular location: Secreted
Pathways (Reactome):
Transport of small molecules: VLDL assembly; VLDL clearance
Signal Transduction: NR1H3 & NR1H2 regulate gene expression linked to cholesterol transport and efflux
Gene Ontology:
Molecular function: fatty acid binding; lipase inhibitor activity; phospholipase inhibitor activity; protein binding; phosphatidylcholine binding; phosphatidylcholine-sterol O-acyltransferase activator activity
Biological process: cholesterol efflux; chylomicron remnant clearance; negative regulation of cholesterol transport; negative regulation of fatty acid biosynthetic process; negative regulation of lipid catabolic process; negative regulation of lipid metabolic process; negative regulation of phosphatidylcholine catabolic process; negative regulation of receptor-mediated endocytosis; negative regulation of triglyceride catabolic process; negative regulation of very-low-density lipoprotein particle clearance; phospholipid efflux; plasma lipoprotein particle remodeling; regulation of cholesterol transport; triglyceride homeostasis; very-low-density lipoprotein particle clearance; high-density lipoprotein particle remodeling; lipid metabolic process; triglyceride metabolic process; very-low-density lipoprotein particle assembly; lipoprotein metabolic process
Cellular component: endoplasmic reticulum; high-density lipoprotein particle; very-low-density lipoprotein particle; chylomicron; extracellular region
Genetic constraint (gnomAD): Loss-of-function variants: 3 observed, 5.06 expected, observed/expected ratio (o/e) 0.59, 90% interval 0.27 to 1.48. That is too few expected variants to judge how well the gene tolerates losing a copy. Missense variants: 120 observed, 99.55 expected, observed/expected ratio (o/e) 1.21, 90% interval 1.04 to 1.4. Synonymous variants: 33 observed, 41.62 expected, observed/expected ratio (o/e) 0.79, 90% interval 0.6 to 1.06.
Homologues: Orthologues: macaque APOC1 (87% identical), chimpanzee APOC1 (80% identical), rabbit APOC1 (69% identical), mouse Apoc1 (67% identical), dog APOC1 (60% identical), guinea pig APOC1 (60% identical), rat Apoc1 (57% identical), zebrafish apoc1 (34% identical).
Diseases named in the same sentence as APOC1 in open-access papers:
APOC1 is named in the same sentence as 195 diseases in open-access papers, as found by Europe PMC text mining. Sharing a sentence is not in itself a finding about the gene and the disease. The quoted sentences say what the papers report.
Alzheimer disease (57 papers, 2009 to 2025). A progressive, neurodegenerative disease characterized by loss of function and death of nerve cells in several areas of the brain leading to loss of cognitive function such as memory and language. "Increasing evidence has shown a correlation between ApoC1 and Alzheimer’s disease; more importantly, ApoC1 is closely associated with cell proliferation, apoptosis, and immune inflammation." (PMID 41294487, 2025). "APOC1 has been implicated in the progress of many diseases such as malignancy, atherosclerosis, and Alzheimer’s disease." (PMID 36891052, 2023). "Alzheimer's disease, diabetes, and atherosclerosis have all been associated to the progression of Apoc1." (PMID 36242090, 2022). "At P<2.5×10−6, we found significant associations with risk of Alzheimer’s disease for APOC1 (Z = 4.84, P = 1.29×10−6) and HLA-DRB1 (Z = 6.80, P = 1.05×10−11) that also passed permutation testing." (PMID 33684137, 2021). "A 4-bp CGTT deletion (H1)/insertion (H2) polymorphism (rs11568822) at the − 317 site in the apoC1 promoter region has been reported to affect apoC1 gene expression and is related to the risks of late-onset Alzheimer’s disease and type III hyperlipoproteinemia." (PMID 29636060, 2018). "Genetic variations in apolipoprotein E (APOE) and proximal genes (PVRL2, TOMM40, and APOC1) are associated with cognitive function and dementia, particularly Alzheimer’s disease." (PMID 29739406, 2018). "For example, a single SNP located 3' of APOC1 (rs4420638) was associated 11 times across GWAS, including association with Alzheimer's disease, lipid-related traits and coronary artery disease (CAD)." (PMID 19161620, 2009). "Although the association of the APOC1 genotype with disease risk may partly result from linkage disequilibrium with APOE, independent associations between APOC1 genotype and Alzheimer’s disease have been observed in various ethnic groups." (PMID 40722932, 2025). "In addition, the model included rs7256200 (APOC1), previously associated with Alzheimer’s disease, and rs1555789087 (TOMM40)." (PMID 37953886, 2023). "In Chinese individuals with late-onset Alzheimer’s disease, APOC1 H2 may work in concert with APOE4 to raise the risk of cognitive deterioration." (PMID 36699066, 2022). "Apolipoprotein CI (APOC1) is a candidate Alzheimer’s disease (AD) gene, and variants of the gene, such as rs11568822, are associated with AD risk and may be functionally related to AD pathophysiology." (PMID 36699066, 2022). "The genomic region chr19:44,902,730–44,915,006, comprising the whole APOE gene as well as its promoter and small parts of TOMM40 and APOC1, was selected as a target region because it includes several SNVs and haplotypes previously linked to Alzheimer’s disease and other age-related diseases." (PMID 33271988, 2020). "A previous study validated the APOC1 SNP rs4420638 as the best proxy for APOE and the most relevant SNP in modulating Alzheimer’s disease risk." (PMID 40722932, 2025). "A study on late-onset Alzheimer’s disease focusing on protein–protein network interactions revealed eight genes with strong associations: APOE, SORL1, APOC1, CD33, CLU, TOMM40, CNTNAP2, and CACNA1C." (PMID 39228919, 2024). "APOC1 and APOE are both located within the 19q13.2 locus and are well-known risk factors for Alzheimer’s disease." (PMID 36882310, 2023). "Note that this larger defined locus showed weak heritability (p = 0.014) for visual network-FC despite the significance of APOC1 in the gene-based GWAS, which would make genetic correlation estimates with Alzheimer’s disease unreliable and uninterpretable." (PMID 36882310, 2023). "Numerous studies link APOC1 to several diseases, such as diabetic nephropathy, type 1 and type 2 diabetes, Alzheimer’s disease, and glomerulosclerosis." (PMID 38136890, 2023). "Previous studies have also shown the association of APOC1/rs11568822 with elevated APOC1 expression, dysbetalipoproteinemia, and higher risk of CHD and Alzheimer’s disease." (PMID 30913229, 2019).
Alzheimer disease (continued). "In addition, it is shown that the APOC1 insertion allele, in combination with APOE ε4, likely served as a potential risk factor for developing Alzheimer’s disease." (PMID 36970281, 2023). "The expression levels of APOC1 are reduced in the frontal cortex of Alzheimer’s disease patients." (PMID 36192455, 2022). "APOC1 and SPP1, prominent in cluster 3, are two of the genes characterizing the disease-associated microglia (DAM) subtype of microglia found in animal models of Alzheimer’s disease and other conditions." (PMID 36466814, 2022). "The APOE ɛ4 allele and minor alleles of rs2075650 TOMM40 and rs12721046 APOC1 variants confer a higher risk of Alzheimer's disease compared with the ɛ4 allele and no minor alleles of these two polymorphisms." (PMID 36330582, 2022). "ApoC1 and ApoE SNPs on TOMM40 are associated with longevity and Alzheimer’s disease risk." (PMID 36233190, 2022). "In the case of Alzheimer’s disease, CR1 and APOC1 appeared to have Tier A evidence of effects, in line with existing literature implicating them in the aetiopathogenesis of condition." (PMID 40281223, 2025). "In T1DM, some of the terms annotated were related to myelin dysregulation (ARHGEF6, CNP, NADK2, PSAP, SLC25A12) and other neurological disorders, such as Alzheimer’s disease (i.e., POA2, APOC1, APOC3, CNP, GSK3B, PON1, PSAP, SELENBP1) or movement disorders." (PMID 39901093, 2025). "In sensitivity analyses using the Alzheimer’s disease GWAS excluding UKB, the estimates for the effect of APOC1 were directionally consistent with our main findings but the confidence intervals were not overlapping." (PMID 40281223, 2025). "The role in inverse comorbidity of cancer and Parkinson’s disease/Alzheimer’s disease was shown for APOE, APOC1, SQSTM1, PSEN1, and SP1." (PMID 37298337, 2023). "For Alzheimer’s disease, allelic heterogeneity was observed in the genomic locus containing NECTIN2, TOMM40, APOE and APOC1, which has been reported before and reflects the fact that different APOE haplotypes ε2, ε3 or ε4 can be risk factors or protective factors for Alzheimer’s disease." (PMID 34326310, 2021). "Notably, we found two genes displaying a negative association between Alzheimer’s Disease (including proxy) trait and Lung Squamous Cell Carcinoma model with Chi2 value of -18.3 (APOE) and -22.7 (APOC1) (see TWAS Trait association table at twas-hub.org/genes/APOE/and twas-hub.org/genes/APOC1/)." (PMID 31608105, 2019).
breast cancer (30 papers, 2009 to 2025). A primary or metastatic malignant neoplasm involving the breast. "APOC1 was demonstrated as a potential diagnostic serum biomarker for breast cancer (BC) through a comprehensive proteomic analysis." (PMID 41294748, 2025). "APOC1 has been identified in a multiprotein index upon postoperative serum proteomic profiles which is associated to metastatic relapse in high-risk breast cancer patients receiving adjuvant chemotherapy." (PMID 20042109, 2009). "Analysis of the individual markers showed that CA1 and NCHL1 levels increased while APOC1 levels decreased in breast cancer." (PMID 36564525, 2023). "The study further revealed that administering an APOC1 peptide to mice with xenografts exhibited an anti-tumor effect, underscoring the significance of APOC1 in breast cancer development." (PMID 38067270, 2023). "APOC1 was reported as an oncogene to promote tumorigenesis and progression of glioblastoma, gastric cancer, hepatocellular carcinoma, breast cancer and so on." (PMID 36536343, 2022). "ApoC1 was described as one of the biomarkers from a panel of five most significant proteins with prognostic value in breast cancer, together with C3a, the component of the complement system, transthyretin, apoA1, and truncated apoH." (PMID 31779116, 2019). "Blood plasma APOC1 is also used in combination with other blood plasma biomarkers to predict breast cancer metastasis." (PMID 29148252, 2018). "Many previous studies have shown that APOC1 may be involved in breast cancer progression and metastasis through mechanisms such as epithelial-mesenchymal transition (EMT) and the MAPK/JNK signaling pathway." (PMID 39877420, 2024). "In another study, plasma levels of APOC1 were reduced in breast cancer patients." (PMID 38067270, 2023). "APOC1 is involved in breast cancer progression via the EMT and MAPK/JNK pathway." (PMID 37305534, 2023). "In addition, it has been proven that breast cancer patients have decreased APOC1 and APOC2 but increased APOC3 levels." (PMID 38067270, 2023). "Additionally, APOC1’s involvement extends to the progression of breast cancer, pancreatic cancer, lung cancer, and prostate cancer." (PMID 38136890, 2023). "A few reports indicated the involvement of apoC1 in breast cancer." (PMID 31779116, 2019). "Importantly, studies suggest that apolipoproteins can inhibit PI3K/AKT/mTOR-mediated angiogenesis in breast cancer, which supports the hypothesis that APOC1 may play a role in the malignant progression and angiogenesis of DLBCL via this signaling pathway." (PMID 39873475, 2025). "However, there is currently limited information regarding the role of APOC1 in breast cancer." (PMID 39877420, 2024). "Subsequent in vitro experiments demonstrated that silencing APOC1 reduced the generation of tumor-associated macrophages (TAMs) with an M2 phenotype while significantly decreasing the proliferation, invasion, and migration of MDA-MB-231 and MDA-MB-468 breast cancer cell lines." (PMID 39877420, 2024). "Research has shown that APOC1 increases vimentin expression and decreases E-cadherin levels, promoting EMT in breast cancer cells." (PMID 39873475, 2025). "Using this methodology, we identified nine proteins—FN1, VWF, PRG4, MMP9, CLU, PRDX6, PPBP (CXCL7), APOC1, and CHL1—that were robustly quantified in serum and showed statistically significant differences between breast cancer patients and healthy controls." (PMID 40940928, 2025). "Thus, inhibiting APOC1 expression may help limit the progression of breast cancer." (PMID 39877420, 2024). "Previous reports have highlighted the significant role of the TGF-β pathway in promoting angiogenesis and progression in breast cancer by inducing EndMT, thereby clarifying the promotive effect of the TGFB2-TGFBR2 on APOC1+ TAMs in tumor progression." (PMID 39232806, 2024).
breast cancer (continued). "The levels of APOC1 and CA1 showed statistically significant differences between 313 patients with breast cancer and 329 participants with BI-RADS C1 or 2 breast imaging or biopsy-proven benign breast lesions." (PMID 36788595, 2023). "In pancreatic cancer, APOA2, APOC1, APOC2, and APOJ have been described, while APOB was found in HCC, bladder, and breast cancer." (PMID 37628784, 2023). "Both measures with high ranks indicated 5 SNPs (SALL1 rs10521222; HLA-DQA1 rs9271608; DUSP1 rs17658229; APOC1 rs4420638; and TRAIP rs2352975) and 3 lifestyles (duration of OC and E + P use and BMI) as the most influential variables for breast cancer." (PMID 33441805, 2021). "TUBA1B+ TAMs, C1QC+ TAMs and VCAN+ TAMs were more prevalent in HER2+ breast cancer, whereas IL1B+ TAMs, SLC40A1+ TAMs and APOC1+ TAMs were more dominant in ER+ breast cancer, which illustrates the heterogeneity of TAM subtypes in various molecular subtypes of breast cancer." (PMID 39232806, 2024). "Despite this crucial discovery, which is echoed in human cases, the specific role of APOC1 in human breast cancer development is still not well-defined." (PMID 38067270, 2023).
atherosclerosis (23 papers, 2011 to 2024). A disease characterized by the build-up of fatty material and calcium deposition in the arterial wall resulting in partial or complete occlusion of the arterial lumen. "Inflammation and atherogenesis are closely interconnected, and apoC1 was implicated as a key factor in the development of LPS-induced atherosclerosis." (PMID 31779116, 2019). "For example, human SNP rs2075650 in Chr 19 has been associated with increased CAD risk and is near the APOE/APOC1 genes whose roles in atherosclerosis are well established." (PMID 26694027, 2015). "As for the similarities in the EV profile of IS and MI patients, we found that APOL1 and APOC1-derived EVs might be related to risk factors such as atherosclerosis." (PMID 33374290, 2020). "Moreover, in humans, high APOC1 content of TRLs is considered a risk factor for early atherosclerosis." (PMID 29346450, 2018). "Despite the possible beneficial use of apoC1 as a CETP inhibitor against atherosclerosis, strategies aiming at inducing very high plasma levels of apoC1 would not be relevant because of the possible hypertriglyceridemic effect." (PMID 36471375, 2022). "In this study, wild type rabbits were compared with transgenic rabbits expressing human apoC1 (HuApoC1-Tg rabbits), in terms of atherosclerosis, plasma lipid and lipoprotein profiles." (PMID 36471375, 2022). "The impact of apoC1 on atherosclerosis via its effect on plasma lipid metabolism was investigated in mice and rabbits." (PMID 36471375, 2022). "In studies performed on normolipidemic, asymptomatic, apparently healthy adult volunteers, the apoC1 content of post-prandial lipoproteins rich in triglycerides was predictive for atherosclerosis, as assessed by the echography of the carotid artery." (PMID 31779116, 2019). "ApoC1 and its effect on atherosclerosis were studied in rabbits by our group more recently." (PMID 36471375, 2022). "In humans, the net impact of apoC1 on atherosclerosis was assessed in several genetic studies." (PMID 36471375, 2022). "These pejorative correlations between plasma apoC1 and atherosclerosis or cardiovascular death were observed in contexts that are critical for atherosclerosis and cardiovascular events, i.e. metabolic syndrome and inflammation on the one hand and heart failure on the other hand." (PMID 36471375, 2022). "LRP1 and ApoC1 accelerate the development of atherosclerosis through different pathways." (PMID 32953262, 2020). "Studies in human APOC1 transgenic mice indicated that they are protected from atherosclerosis." (PMID 31779116, 2019). "Furthermore, we confirm the anti-atherogenic effect of active schistosome infection in an ApoE−/− atherosclerosis mouse model and postulate that this protection is due in part to significant reductions in serum ApoC1." (PMID 30483256, 2018). "Interestingly, LPL (lipoprotein lipase, 1,001 fold), APOE (apolipoprotein E, 778 fold), FABP4 (fatty acid binding protein 4, 680 fold), and APOC1 (apolipoprotein C–I, 614 fold) are atherosclerosis related genes in which activated monocytes play a role." (PMID 23844045, 2013). "Therefore, during the development of atherosclerosis, ApoC1 and Sap in exosomes may synergistically promote the polarization of macrophages to the M1 phenotype." (PMID 37875866, 2023). "ApoC1 is involved not only in many aspects of lipoprotein metabolism, but also in the regulation of inflammatory response and in the biology of some cell components of vascular wall, making its net impact on atherosclerosis difficult to anticipate at first glance." (PMID 36471375, 2022). "Importantly however, it must be borne in mind that beneficial effects of apoC1 on atherosclerosis might be reached on the long term even when keeping its plasma levels within a physiological range as suggested by our studies in transgenic rabbits." (PMID 36471375, 2022).